HNF4A (hepatocyte nuclear factor 4 alpha)
Diseases named in the same sentence as HNF4A in open-access papers (continued):
Sharing a sentence is not in itself a finding about the gene and the disease.
tumor (continued). "The study suggested that HNF4α loss-of-function mutations cause the reduction of HNF4α target gene expression, and, in turn, this may induce hepatic tumorigenesis or tumor growth." (PMID 34771521, 2021). "However, the regulation of HNF4α in the extracellular and intracellular signaling pathways of tumor pathophysiology is relatively complex, and the underlying tumorigenic or tumor-suppressive functions and potential clinical value of HNF4α remain elusive." (PMID 33462379, 2021). "Depletion of HNF4α is a critical determinant of epithelial-to-mesenchymal transition, characterized by loss of the epithelial marker E-Cadherin and induction of the mesenchymal marker Vimentin during tumor progression." (PMID 26157476, 2015). "We sought to understand the mechanism of HNF4α depletion and regulation of tumor development by investigating whether HCV triggers the loss of HNF4α and consequent induction of tumorigenic genes in HCC." (PMID 26157476, 2015). "Together, these findings suggest that the regulatory program associated with HNF4A in normal tissue is disrupted in tumor tissue, a hypothesis in line with previous findings implicating its dysregulation with increased cell proliferation." (PMID 25961905, 2015). "The long term observation of rare polyp initiation in some of the Hnf4α mutant mice could suggest that cumulated defects associated with colonic crypt distortion could eventually lead to tumor initiation under specific circumstances." (PMID 19898610, 2009). "Notably, tumours that exhibited this squamous-like gene expression pattern had reduced expression of colonic epithelial genes and showed changes in chromatin accessibility indicative of loss of HNF4A activity." (PMID 40468074, 2025). "Single-cell analysis identified a previously unrecognized hepatic-differentiated tumor subpopulation expressing master transcription factors HNF1A and HNF4A, which was positioned at the terminal stages of tumor evolution." (PMID 41981779, 2026). "In this issue of Genes & Development, Fort and colleagues (doi:10.1101/gad.352742.125) report HNF4α as a key regulator of hybrid identity states and tumor progression in NKX2-1-positive LUAD." (PMID 40707360, 2025). "Although the mechanistic pathways were not explored in this study, the authors referenced ITLN1’s known roles in modulating HNF4α and β-catenin signaling as possible avenues for its anti-tumor function." (PMID 41149627, 2025). "Our results indicate a dual role of HNF4α in tumor progression, either as a promotor or inhibitor, depending on the pathologic condition of CRAC and the related signaling pathways." (PMID 40277924, 2025). "The extensive reprogramming of gene expression induced by forced expression of HNF4α has relevance in tumoral cells where it can act as tumor suppressor." (PMID 41595461, 2025). "Classical PDAC-specific KLF5 binding sites were enriched for recognition motifs and occupancy of HNF4α, a known master regulator of this tumor subtype 21." (PMID 41241675, 2025). "Compared with those of HH, the ARG1, CPS1, HNF4α, and HNF1α expression levels in tumor cell lines are minimal, if at all." (PMID 40963742, 2025). "Hnf4a and Elovl7 showed higher expression level in the tumor bearing mice, compared to control, suggesting that tumor growth in the lung increased the level of genes involved in lipid metabolism in distal hepatocyte tissues in the KL mouse model." (PMID 40236168, 2025). "These modulators aim to fine-tune HNF4α activity—restoring its tumor-suppressive function in HCC while limiting its tumor-promoting role in PDAC." (PMID 40926269, 2025). "We also found a modest reduction in HNF4A and ATRX expression in liver metastases compared to their matched primary tumours, which provided further support for a progressive loss of colonic identity in advanced disease." (PMID 40468074, 2025).
tumor (continued). "In certain subtypes, particularly those with classical differentiation, overexpression of HNF4α supports tumor progression by promoting metabolic reprogramming—notably enhancing lipogenesis and glycolysis through the SREBP-1c and mTOR pathways." (PMID 40926269, 2025). "We performed gene regulatory network analysis on this dataset and identified enrichment of WNT pathway regulons, specifically LEF1 and TCF7, in the embryonal tumor organoids, while HNF4A was enriched in the fetal-I and II tumor organoids." (PMID 39567475, 2024). "Our results show that HNF4A significantly suppressed tumour growth, at 4 weeks post cell engraftment." (PMID 39165427, 2024). "Remarkably, the deletion of this liver-TE led to a notable upregulation of HNF4A expression and tumor cell growth inhibition, providing compelling evidence for the inhibitory function of this type of DNA elements on HNF4A." (PMID 38965210, 2024). "The same study also showed that the overexpression of HNF4α suppressed tumor growth and liver metastasis in SW480 xenograft model." (PMID 38372868, 2024). "Herein, we show that HNF4A behaves as a tumour suppressor regulating cellular properties such as cell growth, colony and spheroid formation, and invasiveness." (PMID 39165427, 2024). "To this end, we examined HNF4A expression in 2 extra cohorts of patients and performed correlation analyses with clinicopathological parameters including tumor stage and survival." (PMID 39165427, 2024). "The findings from this study suggest the tumor-suppressive activity of the transcription factor hepatocyte nuclear factor 4 alpha (HNF4A)." (PMID 39063215, 2024). "IPA of the human scRNA-seq data from primary tumor and metastasis samples suggested HNF4A as an upstream regulator of LYZ+ cancer cells compared to LYZ- cancer cells." (PMID 39535280, 2024). "In the fetal-I and II tumor organoids, HNF4A expression was consistently observed throughout, while LEF1 expression was generally absent." (PMID 39567475, 2024). "Tumour cells showed enrichment of hepatocyte differentiation‐related TFs HNF4A/G and FOXA1/2,44 and highly expressed targeted genes of these TFs." (PMID 39210544, 2024). "We were able to identify tumor cells that stained strongly for either HNF4A or LEF1, with the staining pattern of the two TFs being mutually exclusive." (PMID 39567475, 2024). "Ingenuity pathway analysis (IPA) of the human scRNA-seq data from primary tumor and metastasis samples suggested hepatocyte nuclear factor 4 alpha (HNF4A) as an upstream regulator of LYZ+ cancer cells compared to LYZ− cancer cells." (PMID 38659853, 2024). "HNF4α, then, promoted HNF1α expression and the interleukin pathway and resulted in a tumor growth effect." (PMID 39768557, 2024). "Taken together, these results help explain the contradictory notion that HNF4α is both a tumor suppressor and at least somewhat oncogenic; the isoforms perform distinct roles in the HCT116 cells by interacting with different co-regulators." (PMID 37635981, 2023). "HNF4A is involved in multiple pathways, and has pro- or anti-tumor effects depending on the cancer type." (PMID 38047081, 2023). "Inhibition of HNF4A resulted in cyclin downregulation, cell cycle arrest, and tumor growth inhibition." (PMID 35132353, 2022). "On the other hand, HNF4A is also known as a major tumor suppressor, and its expression is tightly regulated by HNF1A." (PMID 35327967, 2022). "In cervical cancer, HNF4α inhibits the tumorigenic potential in vivo and induces the tumor cell G0/G1 arrest through suppression of the Wnt/β-catenin pathway." (PMID 36249028, 2022).
tumor (continued). "Promoter P1 HNF4α (P1-HNF4α) is the isoform predominantly expressed in the adult liver and represses the expression of tumor-promoting genes such as c-myc, cyclins, and EMT-related genes in a circadian manner." (PMID 35053606, 2022). "HNF4α is also a key regulator of miR-122 expression in hepatocytes, which acts as a tumor suppressor and represses HCC development." (PMID 35053606, 2022). "We further accessed the expression strength of HNF4A in tumor tissues and adjacent normal tissues of a much larger cohort of cancer patients, by using the GEPIA web server." (PMID 35227282, 2022). "The tumor tissues were composed of hepatocyte nuclear factor 4 alpha (Hnf4α)-positive hepatic lineage cells, which was compatible with histopathological diagnosis of HCC." (PMID 35064244, 2022). "Several nuclear hormone receptors showed changed expression in tumours with high levels of ERBB2 with some being elevated (ESRRA) whereas others were either unchanged (HNF4A) or showed reduced levels (PPARA)." (PMID 36153371, 2022). "Particularly, HNF1α and HNF4α are highly expressed in CRC tumors, the former is linked with tumor malignancy of CRC cells and the latter is considered as a critical risk factor for CRC." (PMID 36497071, 2022). "The tumor-downregulated target proteins of HNF4A, a key transcription factor that drives proximal tubule differentiation, were enriched in proximal tubule bicarbonate reclamation, anion transmembrane transport, and xenobiotic metabolic process." (PMID 35440542, 2022). "HNF4α has been demonstrated to be a tumor suppressor in certain types of tumors but act as an oncogene in other forms of cancers." (PMID 36249028, 2022). "Consistent with reprogramming to liver and tumor cells, respectively, the clonal line expressed endogenous HNF4A, and high levels of the Wnt pathway modulator and stem cell marker LGR5." (PMID 34302118, 2021). "Data in the Ualcan database also showed significantly higher expression levels of HNF4A in tumor tissues than in non-tumor tissues." (PMID 33710810, 2021). "In contrast, another recent study showed that the tumor suppressor ITLN1 promoted HNF4A expression by repressing NF-κB in GC28, and high HNF4A expression showed improved survival outcomes." (PMID 33710810, 2021). "In this context, the pivotal role of HNF4α as a tumor suppressor indicates the design of promising strategies for the treatment of HCC based on the restoration of HNF4α expression and function." (PMID 33462379, 2021). "In this review, we focus on the emerging functional role of HNF4α in a variety of cancers and on the molecular mechanism of HNF4α in the regulation of tumor progression, and we discuss the potential therapeutic uses of HNF4α in cancer." (PMID 33462379, 2021). "These highlights the potential clinical significance of infigratinib‐induced cell differentiation, where tumours with higher expression of HNF4α, albumin and CYP3A4 were less proliferative, therefore reducing disease progression and improving overall survival." (PMID 33179425, 2021). "Both P1 and P2 isoforms of HNF4A are expressed in the small and large intestine, and many studies have suggested a tumor suppressant role for P1-HNF4α and an oncogenic role for P2-HNF4α in CRC." (PMID 34771521, 2021). "Immunofluorescent analysis supported that the heterogeneous tumors express both cytokeratin (CK) and hepatic nuclear factor 4α (HNF4α) in YFP+ tumor cells, indicating CCA and HCC, respectively." (PMID 34083580, 2021). "The possible explanation for the tumor-promoting effect of HNF4α is that the decreased production of ROS and ROS-triggered apoptosis in cancerous cells favors cancer cell survival and proliferation." (PMID 34771521, 2021). "In our study, the HNF4a protein expression in BLCA tissues correlated significantly with the tumor pathology (TNM) grade of the clinicopathological data." (PMID 33628089, 2021).
tumor (continued). "Both HNF1α and HNF4α act as tumor suppressors, and they reduce expression of factors that can trigger tumor development in several types of cells." (PMID 34771521, 2021). "In summary, the role of HNF4α in CRC is complex, depending on the isoform expressed, the tumor microenvironment, and the underlying genomic aberrations." (PMID 34771521, 2021). "HNF4α also inhibits IL-24, a proinflammatory and tumor suppressive pathway, through upregulation of LINC00511 and promotes CRC proliferation, migration, and metastasis." (PMID 34771521, 2021). "Among them, DDIT4 and HNF4A were highly expressed in tumor tissues, whereas ALOX15, IL33, and GDF15 were lowly expressed." (PMID 34434660, 2021). "Researchers previously reported that overexpression of HNF4α can suppress tumor development through downregulation of the Wnt/β-catenin signaling pathway." (PMID 33462379, 2021). "TGFβ inhibits the activity of HNF4α by targeting this protein for proteasomal degradation in tumor cells." (PMID 33462379, 2021). "Studies have revealed that HNF4α inhibits cell proliferation in hepatocytes and abolished HNF4a promotes tumor generation in the liver." (PMID 32023898, 2020). "Downregulated in HCC31–33, HNF4α is considered as a tumor suppressor that represses the development of HCC and inhibit epithelial-mesenchymal transition (EMT), a process that promotes cancer progression and metastasis." (PMID 32770044, 2020). "Different roles of HNF4α have been described, including the tumor suppressive ability that inhibits tumor progress in HCC." (PMID 32023898, 2020). "Another tumor suppressor gene, the Hepatocyte Nuclear Factor 4 alpha HNF4a, plays a key role in the repression of promitogenic genes, the crosstalk with other cell cycle regulators and the regulation of miRNAs." (PMID 33255335, 2020). "The histopathological analyses revealed that the tumours comprised tumour cells exhibiting nuclear HNF4α expression." (PMID 32546802, 2020). "Our data demonstrate that HNF4α downregulation contributes to the formation and development of tumor in xenograft nude mice." (PMID 32023898, 2020). "We also demonstrated that ABAT and ALDH6A1 are directly regulated by a well-known tumor suppressor, transcription factor HNF4A." (PMID 32093682, 2020). "In comparison to non-tumor tissues where different hepatic cells coexist, the tumor tissue consists of mainly the tumor cells (HNF4α positive), and some macrophages." (PMID 32382012, 2020). "The inhibition of hepatocyte proliferation and tumor growth by HNF4α have been well characterized in mice and human tissues." (PMID 32023898, 2020). "Here, we demonstrated that prolonged HBV infection in susceptible host cell line (HepG2-NTCP) or in long-term infected mice can suppress the expression of anti-tumor HNF4α, particularly at later time points." (PMID 32023898, 2020). "The aim of this study was to investigate the effect of HBV on the expression of HNF4α in human hepatocytes and the role of HNF4α suppression in tumor cell proliferation in vivo and in vitro." (PMID 32023898, 2020). "Previously, we demonstrated involvement of the transcription factor HNF4α in human GC tumours, and the developmental signal mediator, WNT5A, as a prognostic GC biomarker." (PMID 30792535, 2019). "Further, Western blotting analysis showed increases in p21 and p27 expression in HNF4α-silenced cell lines, which indicated an activated tumor-suppressive mechanism of HNF4α knockdown." (PMID 30867652, 2019). "Of these factors, HNF4A acts both as a master regulator of liver organogenesis and a tumor suppressor in the liver." (PMID 29899848, 2018).
tumor (continued). "On the contrary, HBL samples contained new isoforms (red circles) located in alkaline regions of the 2D gel, suggesting that posttranslational modifications that occur in aggressive HBL result in the neutralization of the tumor suppressor activity of HNF4α." (PMID 30271949, 2018). "Hepatocyte nuclear factor 4 alpha (HNF4α) is regulated by different promoters to generate two isoforms, one of which functions as a tumor suppressor." (PMID 30341289, 2018). "BALB/c nude mouse models with xenografted human SGC7901 cells, Lenti-GFP and LV-HNF4α-SGC7901 cells were employed to evaluate the effect of HNF4α on tumor growth in vivo." (PMID 30405404, 2018). "An HNF4A-microRNA-194/192 signaling axis was suggested to influence glucose metabolism, cell adhesion and migration, tumorigenesis and tumor progression, as well as epigenetic regulation in a recent study." (PMID 30463528, 2018). "Consistent with in vitro experiments, BBR downregulated HNF4α, WNT5A, and cytoplasmic β-catenin expression in somatic tumor tissues, the same effect as knocking out HNF4α gene." (PMID 30405404, 2018). "Histopathologic analysis showed that approximately 80% of the tumor burden in KrasLSL-G12D/+; Nkx2-1F/F; Foxa1F/F; Foxa2F/F mice consisted of mucinous HNF4α-positive adenocarcinomas." (PMID 30475207, 2018). "In this article, we identified that anti-apoptosis related gene Bcl-2, and tumor suppressor protein PTEN participated in this IL-23 and HNF4α mediated tumor progression." (PMID 29983862, 2018). "Since then, diverse roles for HNF4α have been described, including its ability to function as a tumor suppressor, suppressing several genes (such as cyclin D1, CCND1) known to be causal for HCC initiation, growth, or progression." (PMID 30341289, 2018). "Hepatocyte nuclear factor 4 alpha (HNF4α) is a master regulator of liver-specific gene expression with potent tumor suppressor activity, yet many liver tumors express HNF4α." (PMID 30341289, 2018). "For example, we showed that the mRNA levels of transferrin (TF), Apolipoprotein A1 (APOA1) and hepatocyte nuclear factor 4-alpha (HNF4α) were significantly altered in AA liver (cirrhotic) and tumor samples compared to CA." (PMID 28938650, 2017). "Like many important oncogenes and tumor-suppressors, HNF4α is an orphan nuclear receptor that lacks well-defined activating ligand; how to modulate these oncogenes and tumor-suppressors to treat cancer is a huge challenge." (PMID 29234104, 2017). "Our data showed that HNF4α expression was up-regulated in gastric carcinogenesis and its expression contributes to in vitro gastric cell proliferation and in vivo tumor growth." (PMID 26870992, 2016). "Consistently, reduced HNF4α levels correlated well with larger tumor size (P = 0.0001) and advanced tumor stage (P = 0.022)." (PMID 27050273, 2016). "Tumor growth was significantly inhibited for cells with HNF4α knockdown (Hsh) compared to control group (NC)." (PMID 26870992, 2016). "Our present study found that HNF4α works as a tumor promoter by transactivating exo70, which increases Cdc2 expression leading to G2/M transition." (PMID 26848864, 2016). "In particular, the presence of TGFβ in the tumor niche impaired HNF4α activity by inducing the displacement of the ectopic protein from its target gene promoters through the inactivation of GSK-3β activity." (PMID 28943628, 2015). "The whole described tumor-suppressing functions of HNF4α indicate that this protein represents a good candidate for the extensive reprogramming of tumor cells and, therefore, a promising tool for gene therapy of HCC." (PMID 28943628, 2015). "miR-629–5p also promotes cell growth, has been found to be important for hepatocarcinogenesis via HNF4a repression, and targets the NBS1 DNA tumor susceptibility gene." (PMID 25760330, 2015).